RNU5B-2P (RNA, U5B small nuclear 2, pseudogene)
Gene: Small nuclear RNA gene on chromosome 3 (40,498,891 to 40,499,003, reverse strand). Ensembl gene ENSG00000199906.
Homologues: Orthologues: chimpanzee U5 (97% identical), macaque U5 (82% identical). Paralogues in human: RNU5A-2P (73% identical), RNU5E-10P (73% identical), RNU5A-5P (72% identical), RNU5A-3P (71% identical), RNU5E-5P (71% identical), RNU5A-6P (70% identical), RNU5B-4P (70% identical), RNU5A-4P (69% identical), RNU5A-8P (69% identical), RNU5E-4P (69% identical), RNU5E-7P (69% identical), RNU5E-8P (68% identical), and 13 more.